RNU6-1027P (RNA, U6 small nuclear 1027, pseudogene)
Gene: Small nuclear RNA gene on chromosome 2 (229,973,315 to 229,973,421, forward strand). Ensembl gene ENSG00000206725.
Homologues: Orthologues: chimpanzee U6 (98% identical), macaque U6 (93% identical), pig U6 (82% identical), pig U6 (78% identical), rat LOC120095359 (77% identical), mouse Gm22883 (74% identical), pig U6 (71% identical). Paralogues in human: RNU6-25P (89% identical), RNU6-1 (88% identical), RNU6-2 (88% identical), RNU6-20P (88% identical), RNU6-35P (88% identical), RNU6-364P (88% identical), RNU6-38P (88% identical), RNU6-3P (88% identical), RNU6-4P (88% identical), RNU6-5P (88% identical), RNU6-6P (88% identical), RNU6-73P (88% identical), and 1288 more.